IL6R (interleukin 6 receptor)
Diseases named in the same sentence as IL6R in open-access papers (continued):
Sharing a sentence is not in itself a finding about the gene and the disease.
blood disorders (1 paper, 2025). "To explore the possible mechanism of SARS-CoV-2-induced blood disorders and inflammation by elevating IL-6 and IL-17, we carried out molecular docking to investigate PPIs between SARS-CoV-2 spike protein (S) and either unliganded IL-6R and IL-17R or complex forms IL-6/IL-6R and IL-17/IL-17R." (PMID 41184328, 2025).
colon polyps (1 paper, 2016). "A recent paper showed that enhanced IL-6 in Nlrx1−/− mice is consequential, as anti-IL6R therapy completely reduced colon polyps in these animals." (PMID 27105514, 2016).
IL6R also shares sentences with these, for which no sentence is quoted: allergic asthma (5 papers); bipolar disorder (5); multiple sclerosis (5); ulcerative colitis (5); acute respiratory distress syndrome (4); Allergy (4); chronic lymphocytic leukemia (4); oral squamous cell carcinoma (4); peritonitis (4); pneumonitis (4); acute myocardial infarction (3); bacterial sepsis (3); congestive heart disease (3); fibrosis (3); Hypercholesterolemia (3); macular edema (3); periodontal disease (3); renal cell carcinoma (3); retinopathy (3); acute coronary syndrome (2); brain tumor (2); bronchitis (2); Diabetic Nephropathy (2); diabetic retinopathy (2); eosinophilia (2); frontotemporal dementia (2); fungal infection (2); glaucoma (2); hemophagocytic lymphohistiocytosis (2); idiopathic multicentric Castleman disease (2).
A further 172 diseases each share a sentence with IL6R in 2 papers or fewer.